IGF1 (insulin like growth factor 1)
Diseases named in the same sentence as IGF1 in open-access papers (continued):
Sharing a sentence is not in itself a finding about the gene and the disease.
gestational diabetes (27 papers, 2016 to 2025). Carbohydrate intolerance first diagnosed during pregnancy. "In a prospective longitudinal study, IGF-1 concentrations were positively related to subsequent risk of gestational diabetes." (PMID 36088507, 2022). "In addition to the potential mechanism of action through birthweight, a recent meta-analysis found that gestational diabetes was consistently associated with higher maternal insulin-like growth factor-1 (IGF-I) concentrations." (PMID 36088507, 2022). "The insulin resistance of pregnancy is exacerbated by maternal obesity, excessive gestational weight gain, and gestational diabetes, resulting in even lower maternal levels of adiponectin and higher levels of insulin, leptin, and IGF-1." (PMID 37764824, 2023). "There is an increased production of fetal insulin, insulin-like growth factor 1, and leptin, resulting in the stimulation of fetoplacental growth for mothers with gestational diabetes." (PMID 35631166, 2022). "Most of the studies on insulin and IGF-1 levels are focused on women with gestational diabetes, with a primary focus on maternal health and newborn parameters." (PMID 34371854, 2021). "A statistically positive correlation between the concentration of IGF-1 in umbilical cord serum of newborn babies born to women with gestational diabetes and the length of a baby after its birth was observed." (PMID 33053704, 2020). "Similarly, log cord serum IGF-1 were independently associated with BW and BL in the multivariable regression analysis, after adjusting for gestational age, delivery mode, multiple gestation, pregnancy induced hypertension, gestational diabetes, infant’ BMI, and log cord serum leptin." (PMID 32607107, 2020). "Log cord serum leptin were independently associated BW, BL, and HC in the multivariable regression analysis, after adjustment for gestational age, delivery mode, multiple gestation, pregnancy induced hypertension, gestational diabetes mellitus, infant’s BMI, and log cord serum IGF-1." (PMID 32607107, 2020). "Therefore, further comprehensive research iswarranted to explore the relationships between serum levels of sex hormone-binding globulin (SHBG), insulin-like growth factor-1 (IGF-1), and cortisol and gestational diabetes mellitus (GDM) in greater depth." (PMID 39876919, 2024). "IGF-1 is also involved in pregnancy complications, including uterine growth restriction, gestational diabetes mellitus, and PE, but the precise role of IGF-1 in pregnancy is not clear." (PMID 39768370, 2024). "Several studies reported that cord blood IGF-1 levels were similar in infants of non-diabetic mothers and mothers with gestational diabetes." (PMID 37764824, 2023). "The study also shows what the hormonal balance (insulin and IGF-1) looks like in women with a physiological course of pregnancy (without gestational diabetes), while most insulin and IGF-1 studies are conducted in women with gestational diabetes." (PMID 34371854, 2021).
Sleep apnea (27 papers, 2013 to 2026). An intermittent cessation of airflow at the mouth and nose during sleep is known as sleep apnea. "Reduced levels of IGF1 (insulin-like growth factor 1) were found to be associated with poor sleep quality, excessive daytime sleepiness, and sleep apnea." (PMID 35958162, 2022). "The authors also reported that the factors associated with sleep apnea were age, male sex, IGF1, body mass index (BMI), and disease duration." (PMID 33389987, 2021). "Concerns have been raised regarding the association of hGH with excessive elevations in IGF-1, sleep disordered breathing, scoliosis, alterations in glucose metabolism, and sudden death." (PMID 23962041, 2013). "Among the mechanisms involved are excess GH and IGF-1, which generate an expansion of extracellular fluid volume, promote sodium and water retention at the renal level, increase vascular resistance, and are associated with the possible presence of sleep apnea." (PMID 40142714, 2025). "This raises concerns about the safety issues related to high IGF-1 levels, as high levels of IGF-1 have been associated with lymphoid hyperplasia and this might increase the risk of sleep apnea." (PMID 36564648, 2023). "Conversely, a decrease in sleep duration and an increase in indices of sleep apnea severity as measured by the apnea + hypopnea index (AHI) and the degree of oxygen desaturation, are associated with lower levels of GH/IGF-1." (PMID 32655494, 2020). "Therapy with hGH potentially worsens sleep-disordered breathing because increased IGF-1 levels lead to lymphoid hyperplasia." (PMID 28943608, 2015). "HGH therapy potentially worsens sleep disordered breathing because increased IGF-1 levels lead to lymphoid hyperplasia." (PMID 23962041, 2013). "It is worth noting that the initial weeks of rhGH treatment may lead to worsened sleep-related breathing disorders (SRBDs) and adenoid hypertrophy, possibly due to high levels of insulin-like growth factor 1 (IGF-1) after starting rhGH." (PMID 38200464, 2024). "The originality of our data is to demonstrate that severe sleep apnea was the single comorbidity associated with low IGF-1 values, independent of BMI or waist circumference." (PMID 32655494, 2020). "In addition, it is prudent to titrate hGH dosing to keep IGF-1 levels in the normal range to minimize the possibility of lymphoid hyperplasia and, while on therapy screen for signs and symptoms of worsening sleep apnea." (PMID 28943608, 2015). "Thus, both adiposity and sleep apnea seem to synergistically predict low levels of IGF-1 and thus could participate together toward cardio-metabolic risk." (PMID 32655494, 2020). "In cases where there is a deterioration of sleep-disordered breathing, snoring, or enlargement of tonsils and adenoids, additional evaluations such as ear, nose, and throat assessments, PSG, and IGF-1 measurements are deemed necessary." (PMID 38200464, 2024). "While the association between IGFBP-3 and sleep-related breathing disorders (SRBDs) in PWS remains unexplored, our study indicates that the heightened levels of IGF-1 and IGFBP-3 resulting from rhGH treatment do not adversely affect SRBDs." (PMID 38200464, 2024).
Arthritis (26 papers, 2006 to 2026). Inflammation of a joint. "Administration with curcumin reversed the CIA-induced increase in arthritis scores, hind paw edema, and loss of appetite, while these effects were rescued by insulin-like growth factor 1, the upstream cytokine of PI3K/AKT." (PMID 35609329, 2022). "Cartilage loss is a hallmark of arthritis and follows activation of catabolic processes concomitant with a disruption of anabolic pathways like insulin-like growth factor 1 (IGF-1)." (PMID 16603065, 2006). "Future research will delve into the pathological pathways and mechanisms that connect IGF-1, BMI, and arthritis, as well as the determination of the quantitative ranges for IGF-1 levels and BMI concerning these diseases." (PMID 39050250, 2024). "We examined the anti-arthritogenic properties of IGF-1-modified amniotic mesenchymal stem cells (AMM/I) in an experimental arthritis model." (PMID 38674027, 2024). "Effective strategies for delivering IGF-1 to chondrocytes and the cartilage matrix are crucial for its clinical application in the treatment of arthritis." (PMID 38674027, 2024). "Building on this advancement, we explored the anti-arthritogenic potential of IGF-1 gene-edited amniotic MSCs (AMM/I) in an experimental arthritis model with cartilage damage." (PMID 38674027, 2024). "In conclusion, our findings suggest that IGF-1 gene-edited human AMM represent a novel alternative therapeutic strategy for the treatment of arthritis." (PMID 38674027, 2024). "Our findings align with those of previous research, as we observed a downregulation of Th-17 cells and inflammatory factors following the administration of AMM/I, suggesting the potential suppression of arthritis through the action of IGF-1 derived from AMM/I." (PMID 38674027, 2024). "On the other hand, in chronic inflammatory conditions, such as experimental arthritis, plasma concentrations of IGF-1 and GH as well as pituitary GH mRNA are decreased." (PMID 34502376, 2021). "Thus, spatial transcriptomics maps diverse cell types in TMJ and reveals a remodeling of synovial fibroblast-immune microenvironment via the Igf1-Il33 axis, which drives arthritis pain with therapeutic potentials." (PMID 41498747, 2026). "Notably, the GWAS data for IGF-1 and BMI come from European populations, with approximately 85% of the arthritis GWAS data originating from individuals of European ethnicities." (PMID 39050250, 2024). "In addition, in experimental arthritis, rhGH increases body weight as well as hepatic and serum concentrations of IGF-1." (PMID 34502376, 2021). "Moreover, IL-7R and IGF-1 remained significantly associated even after correction for known predictors (ACPA, CRP, imaging-detected subclinical joint inflammation; p = 0.039, p = 0.005, respectively)." (PMID 33168080, 2020). "In dogs with arthritis, active forms of C1r and C1s, along with reduced concentrations of IGFBP-5, IGFBP-3 and IGF-1, were present in their synovial fluid." (PMID 38002958, 2023). "Curcumin reduced arthritis index and foot swelling in CII-stimulated mice, while such effect was further rescued by IGF-1." (PMID 35609329, 2022). "Thus, smoking-induced low levels of IGF1 and leptin may support the aberrant T-cell formation at the preclinical stage of arthritis, in the poor bone remodelling and progressive joint damage in the overt arthritis, and for the early cardiovascular mortality in RA." (PMID 27041823, 2016). "The current lack of detailed stratification in arthritis data, particularly regarding severity, restricts the exploration of the IGF-1 and OA relationship." (PMID 39050250, 2024). "Second, after establishing a mouse model of RA, the effects of curcumin and curcumin + insulin-like growth factor 1 (IGF-1), the upstream cytokine of PI3K/AKT, on collagen-induced arthritis (CIA) were assessed by evaluating arthritis index scores and degree of paw swelling." (PMID 35609329, 2022).
Arthritis (continued). "Indeed, there appears to be excellent evidence that growth restriction with chronic inflammation, including arthritis, is the result of suppression of IGF-1 production and activity, independent of GH, and in response to IL-6." (PMID 16603065, 2006). "The previous investigation revealed that insulin-like growth factor 1 (IGF-1) could upregulate the synthesis of ChS-rich aggregating proteoglycans even at the relatively high concentration of inflammatory factors such as IL-1 and TNF-α, indicating that IGF-1 has the potential to ease arthritis." (PMID 36032667, 2022). "In a rat RA model, both circulating and skeletal muscle IGF-1 were decreased, the animals showed lower muscle mass, and subcutaneous injection of IGF-1 (100 μg/kg; twice daily for 12 days) increased body and hindlimb muscle weight without changing arthritis." (PMID 32858949, 2020).
diabetic nephropathy (26 papers, 2002 to 2024). "Intriguingly, insulin-like growth factor-1 (IGF-1) has been reported to be implicated in podocyte regeneration in diabetic nephropathy, suggesting its involvement in the pathology of DM." (PMID 32544883, 2020). "Insulin stimulates the production of insulin-like growth factory 1 (IGF-1) by vascular smooth muscle cells and other cell types, which have been implicated in the development of diabetic kidney disease." (PMID 23690758, 2013). "Thus, downregulation of this pathway in mesangial cells in insulin deficiency leads to increased actions of IGF1 on matrix production, glomerular enlargement, and progression of diabetic nephropathy." (PMID 34943879, 2021). "Insulin-like-growth factor-1 (IGF-1) is the ligand for insulin-like growth factor-1 receptor (IGF-1R), and the roles of IGF-1/IGF-1R in diabetic nephropathy (DN) are well-characterized previously." (PMID 37034500, 2023). "In diabetic kidney disease, elevated levels of IGF-1 result in Snail1 upregulation and profibrotic effects." (PMID 36361979, 2022). "Pearson correlation analysis was used to explore the close degree of serum IGF-1 and clinical indicators in patients with diabetic kidney disease." (PMID 36568065, 2022). "Early studies have shown that elevated serum levels of IGF-1 can influence the early pathological processes of diabetic kidney disease, such as glomerular enlargement, renal hyperfiltration and renal hypertrophy." (PMID 36568065, 2022). "GH and IGF-1 play a significant role in the early development of diabetic nephropathy, as well as in compensatory kidney hypertrophy after unilateral nephrectomy." (PMID 34943879, 2021). "Mesangial cells isolated from experimental models of diabetic nephropathy exhibit altered IGF1 synthesis, IGF1 pathway activation, and higher IGF1R expression and activation compared with controls." (PMID 34943879, 2021). "Glomerular hypertrophy is observed in early diabetic nephropathy, and the GH/IGF-1 axis plays a major role in its development." (PMID 31540583, 2019). "IGF-1 is transiently increased in the kidney before renal hypertrophy in early diabetic nephropathy." (PMID 31540583, 2019). "Collectively, our findings support the notion that catalpol exerts its therapeutic effects on diabetic nephropathy possibly by down-regulating Grb10 expression and the subsequent activation of IGF-1/IGF-1R signaling." (PMID 26986757, 2016). "The sequestered IGF1 induces the glomerular hypertrophy and renal hyperfiltration that is characteristic of early diabetic nephropathy." (PMID 23781310, 2012). "Insulin-like growth factor-1 (IGF-1) is a growth factor crucial for maintaining the structure and function of glomeruli and renal tubular cells, playing a pivotal role in the pathogenesis of diabetic nephropathy (DN)." (PMID 38972889, 2024). "Notably, dysregulation of the IGF1 system has been described in several kidney diseases, including diabetic nephropathy, polycystic kidneys and proteinuric kidney diseases." (PMID 34944624, 2021). "Several mechanisms have been proposed to explain the role of GH and IGF1 in diabetic nephropathy." (PMID 34943879, 2021). "One hypothesis is that in diabetic kidney disease there is an IGF-independent primary increase in IGFBP1 concentration in the kidney that subsequently traps IGF1 within the renal glomerulus." (PMID 23781310, 2012). "It has been speculated that IGF1-mediated increases of nitric oxide synthesis contribute to glomerular hyperfiltration in the early stages of diabetic kidney disease." (PMID 23781310, 2012). "Our results suggest that elevated Grb10 expression may play an important role in the pathogenesis of diabetic nephropathy through suppressing IGF-1/IGF-1R signaling pathway, which might be a potential molecular target of catalpol for the treatment of this diabetic complication." (PMID 26986757, 2016).
diabetic nephropathy (continued). "IGF-1 and FGF drive proximal tubule hypertrophy and hyperplasia, a process seen in both diabetic nephropathy and in the renal repair phase after AKI." (PMID 37467896, 2023). "In humans, there is a well-established correlation between the activity of the growth hormone (GH)/insulin-like growth factor 1 (IGF-1) axis and renal conditions such as hypertrophy, microalbuminuria, and glomerulosclerosis, which mirror the development of diabetic nephropathy." (PMID 38673935, 2024). "Furthermore, we analyzed insulin-like growth factor 1 (IGF-1) and IGF-binding protein 1 (IGFBP-1) since the IGFBP-1 and IGF1 have been shown to be associated with diabetes nephropathy independent of the degree of albumin." (PMID 22400116, 2012). "Studies on GH-IGF1 axis in CKD and diabetic nephropathy showed that systemic levels of GH and IGF1 do not always reflect their local levels and actions in the kidney." (PMID 34943879, 2021).
triple-negative breast carcinoma (26 papers, 2011 to 2025). An invasive breast carcinoma which is negative for expression of estrogen receptor (ER), progesterone receptor (PR), and human epidermal growth factor receptor 2 (HER2). "Calorie restriction (CR) inhibits triple-negative breast cancer (TNBC) progression in several preclinical models in association with decreased insulin-like growth factor 1 (IGF1) signaling." (PMID 37686596, 2023). "While an increased activity of the IGF1 pathway is commonly observed in triple negative breast cancer, we observed substantial ethnicity-associated heterogeneity within TNBC samples." (PMID 24260093, 2013). "In the present study, we report a potential IGF-1 induced metabolic programming of de novo fatty acid synthesis in triple negative breast cancer cells through FASN." (PMID 36096767, 2022). "Based on these current findings, an IGF-1-mTORC1-SRPK2 axis contributes to lipogenic metabolic regulation through FASN in triple negative breast cancer cells." (PMID 36096767, 2022). "In triple negative breast cancer, cell growth and fokal adhesion formation are triggered by an IGF1/IGF1R/FAK/Akt/YAP signaling cascade." (PMID 34440844, 2021). "The IGF-1/IGF-1R/YAP pathway was reported to promote growth effects in triple-negative breast cancer (TNBC) cells." (PMID 34359714, 2021). "For example, CAF-derived CXCL12 and insulin-like growth factor 1 (IGF1) can promote the survival and outgrowth of highly invasive and metastatic triple-negative breast cancer cells in the bone marrow." (PMID 28356139, 2017). "Furthermore, IGF-1 levels are higher among African-American women and triple negative breast cancer is more frequent among African-American women." (PMID 25062088, 2014). "Current research on triple-negative breast cancer includes anti-tumor-related pathways against IGF1, promotion of tumor cell death, and targeting the IGF-1/IGF-1R signaling axis for the treatment of TNBC." (PMID 41209699, 2025). "Its expression in triple-negative breast cancer cells is enhanced by the transcription factor RUNX2, and both, BSP and RUNX2 are under control of IGF-1 and TGFβ1." (PMID 30805306, 2019). "In triple-negative breast cancer, the tumor subtypes rich in CAFs are more prone to bone metastasis, which is related to CXCL12 (C-X-C motif chemokine ligand 12) and IGF1 (insulin-like growth factor-1) cytokines and the CCL4-CCR5 (C-C motif chemokine ligand 4-C-C motif chemokine receptor 5) axis." (PMID 34877360, 2021). "In triple-negative breast cancer, CAFs were described to secrete C-X-C motif chemokine ligand 12 (CXCL12) and insulin-like growth factor-1 (IGF1) factors that promote the expansion of high metastatic clones with high Src activity, a known predictor of bone metastasis." (PMID 32793478, 2020). "In addition to previous data showing that the IGF1 pathway may be a sensitive target in TNBC, this study suggests that African American patients with triple negative breast cancer represent an understudied group of patients who may benefit from drugs targeting the IGF1 pathway." (PMID 24260093, 2013).